ASPN (asporin)
Diseases named in the same sentence as ASPN in open-access papers (continued):
Sharing a sentence is not in itself a finding about the gene and the disease.
breast carcinoma (continued). "Although high asporin expression may serve as a good prognostic marker for tumor grades 1 and 2, the opposite can be observed in high-grade breast cancer." (PMID 27409832, 2016). "We next sought to examine whether CAFs would express asporin following their isolation from cancer tissue and whether they would react similarly to NBFs when exposed to the CM of breast cancer cells." (PMID 26327350, 2015). "Other experiments showed that TGF-β1 secreted by breast cancer cells induces asporin expression in breast fibroblasts, and that asporin, in turn, inhibits TGF-β1-mediated induction of the epithelial to mesenchymal transition and stemness in breast cancer cells." (PMID 26327350, 2015). "Next, they showed that breast fibroblasts secrete asporin when exposed to conditioned medium from some human breast cancer cell lines (breast cancer cells adapted to grow continuously in the laboratory; conditioned medium is the solution in which cells have been grown)." (PMID 26327350, 2015). "If these findings are confirmed, methods for increasing asporin expression in the stromal tissues of triple negative breast cancer could be a promising strategy for targeted therapy for this group of breast cancers, which currently have a poor prognosis." (PMID 26327350, 2015). "Interestingly, asporin functional studies in breast cancer is another story." (PMID 33614646, 2021). "Thus, we sought to verify how asporin expression correlates with breast cancer patient outcome." (PMID 26327350, 2015). "Indeed, the evaluation of two independent and well-established signatures of CSCs, namely ALDH positivity (general) and the abundance of the CD44high/CD24low (breast cancer-specific) population, confirms that asporin-expressing tumors have on average (two signatures together) 50% fewer CSCs." (PMID 26327350, 2015). "And TAGLN, ASPN, KRT19 and MGST1 have important roles in the prognosis, invasion, metastasis and drug resistance of breast cancer." (PMID 37470685, 2023). "Thus, asporin expression might provide a new prognostic marker for breast cancer." (PMID 26327350, 2015). "A retrospective IHC study performed on human breast carcinoma (n = 180) demonstrates that asporin expression is lowest in TNBC and HER2+ tumors, while HR+ tumors have significantly higher asporin expression (4-fold; p = 0.001)." (PMID 26327350, 2015). "In tumor tissues, ASPN is mainly detectable in the stroma secreted by CAFs and not by cancer cells, while the majority of breast cancer cells independently of their receptor status do not express ASPN." (PMID 36358747, 2022). "Unlike breast cancer, where ASPN was found to play dual opposing roles, in GC patients high tumor-specific expression of ASPN exhibited worse clinico-pathological parameters and survival rates." (PMID 34379688, 2021). "Downregulation by shRNA inhibited invasion of Hs578T as well as of CAFs and T47D cells while invasion of asporin-negative MDA-MB-231 and BT549 breast cancer cells through collagen type I was enhanced by recombinant asporin." (PMID 27409832, 2016). "In breast cancer Hs578T cells, BMP4 slightly downregulated asporin and phosphorylation of focal adhesion kinase (FAK) at tyrosine 397 (2.4 and 2.1 mean fold downregulation, respectively), while BMP2 did not cause any consistent changes (1.2 mean fold downregulation)." (PMID 27409832, 2016). "None of the human breast cancer cell lines tested showed detectable asporin expression levels (both protein and mRNA)." (PMID 26327350, 2015). "Employing immunohistochemistry (IHC) analysis, we report, to our knowledge for the first time, that asporin is overexpressed in the stroma of most human breast cancers and is not expressed in normal breast tissue." (PMID 26327350, 2015). "Using a technique called immunohistochemistry, the researchers first showed that asporin is highly expressed in the stroma of most human breast cancers but not in normal breast tissue." (PMID 26327350, 2015).
breast carcinoma (continued). "Notably, CAF‐derived asporin inhibits TGF‐β signaling and EMT in breast cancer cells, and overexpression of asporin in patient‐derived normal mammary fibroblasts cotransplanted with MDA‐MB‐468 xenograft reduced tumor growth and metastasis." (PMID 29280568, 2018).
keloid (12 papers, 2010 to 2024). An irregularly shaped, elevated mark on the skin caused by deposits of excessive amounts of collagen during wound healing. "Overexpression of ASPN inhibits fibroblast activity and differentiation into mature myofibroblasts, which quickly alter the extracellular matrix, thereby resulting in keloid formation and invasion." (PMID 37869159, 2023). "The specific expression of ASPN was confirmed in keloid by RT-qPCR, immunohistochemistry and Western blot analysis; ASPN was strongly expressed in keloids, but the expression signal was negative or weakly positive in normal skin." (PMID 36394011, 2022). "In this study, keloid fibroblasts and tissues were transfected with ASPN-siRNA to decrease the expression of ASPN protein." (PMID 36394011, 2022). "The results of the scratch assay indicated that silencing ASPN inhibited the migration of keloid fibroblasts." (PMID 36394011, 2022). "The boxplot showed significantly higher expression of ASPN in the keloid group than in normal skin.In analyzing the sensitivity and specificity of ASPN gene, the area under the ROC curve was 0.984." (PMID 36394011, 2022). "With the expression of ASPN protein greatly reduced in keloid fibroblasts and nude mice allografts after treatment with si-ASPN, the collagen and fibroblasts were also uniform, thinner, parallel and regular." (PMID 36394011, 2022). "ASPN also showed a high level of significant fold change (approximately 96-fold upregulation) in keloid margins." (PMID 20418938, 2010). "The expression of ASPN gene in keloid group and normal control group were analyzed." (PMID 36394011, 2022). "Finally, we can conclude that ASPN is very complex in keloids, but as research progresses, ASPN has the potential to be a promising biomarker and therapeutic target for keloid formation." (PMID 36595867, 2022). "The si-ASPN/nanoparticle complexes may therefore be a useful kind of gene therapy for the treatment of keloid." (PMID 36394011, 2022). "ASPN is identified in cancerous tissue, pathological cardiac tissue, articular cartilage, keloid, and fibrotic lung tissue, and it has a role in the development of cancer, cardiovascular, bone and joint, keloid, and pulmonary fibrosis by interfering with collagen metabolism." (PMID 36595867, 2022). "This suggests that ASPN siRNA/nanoparticles may provide a novel therapeutic strategy for the management of keloid." (PMID 36394011, 2022). "Research proves that keloid tissues had considerably higher levels of ASPN protein expression and that the Wnt signaling pathway maybe play an important role in keloid development." (PMID 36394011, 2022). "Second, we only investigated the effect of ASPN proteins on the regulation of keloid." (PMID 36394011, 2022). "This suggests that the ASPN gene may control the developmental rate of keloids by modulating the Wnt signaling pathway." (PMID 36394011, 2022). "ASPN is upregulated in keloid margin biopsy specimens compared with that from adjacent healthy skin, indicating it may serve as a potential biomarker for keloid disease." (PMID 32063855, 2019). "Likewise, comparative mass spectrometry-based proteomic analysis of keloids and healthy skin has shown that ASPN expression was significantly increased in keloid scars." (PMID 32063855, 2019). "Therefore, it was hypothesized that the ASPN-siRNA/nanoparticle combination would be effective in inhibiting the growth of keloid." (PMID 36394011, 2022). "In our present study, we screened bone/cartilage-related genes (COMP, ASPN, COL5A2, COL10A1, and COL11A1), transcription factor (FOXC1), and miRNA (miR-335-5p) in major fibrotic skin diseases including keloid and SSc." (PMID 37082197, 2023). "The fact that some proteoglycans related to skin mechanical forces (e.g., ASPN, VCAN, and OMD) were also overexpressed in keloids proved the interaction between skin mechanical disorder and keloid formation again." (PMID 35435317, 2022). "Therefore, the ASPN may play an important role in the formation of keloids." (PMID 36394011, 2022).
keloid (continued). "One of the characteristics of the mesenchymal fibroblasts in keloid is the high expression of secretory proteins such as POSTN, COMP, COL11A1, ASPN, and COL5A2." (PMID 34140509, 2021). "The top 50 DEGs in lesional versus normal skin comparison included products related to fibrosis and cartilage/bone-differentiation (ADAM12, ASPN, COL10A1, COL11A1, FBN2), previously reported to be dysregulated in keloids." (PMID 33329590, 2020). "Genes involved in extracellular matrix formation including COL1A1, COL3A1, POSTN, COL1A2, FN1, and ASPN were significantly upregulated in keloid compared to the normal skins." (PMID 35990663, 2022). "However, the results of the present study revealed for the first time the downregulation of five genes (ANXA1, ASPN, IGFBP7, LGALS1, and PTN) which is in contrast to the upregulation of the same genes in African and Caucasian keloid samples." (PMID 32085797, 2020). "A statistically significant (P < .05) differential expression and a fold change of more than 2 were determined between keloid margin and internal control biopsy samples for 10 genes, including ACAN, ASPN, C5orf13, HIF1A, IGFBP7, INHBA, LGALS1, PTN, SERPINH1, and TNFAIP6." (PMID 20418938, 2010).
prostate carcinoma (12 papers, 2016 to 2025). A carcinoma that arises from epithelial cells of the prostate gland. "In this study, we sought to identify the molecular interactions between cancer-associated stromal ASPN and prostate cancer cells." (PMID 40857406, 2025). "Elevated ASPN expression in the TME of localized prostate cancer is associated with increased grade and worse oncologic outcomes, including metastasis." (PMID 40857406, 2025). "Asporin contains 380 amino acids and its D-repeat polymorphisms (residues 8–19) in the N-terminus are correlated with osteoarthritis and metastatic recurrence of prostate cancer." (PMID 35600399, 2022). "Studies of ASPN in pancreatic, gastric and prostate cancer drew a consistent opinion that ASPN could promote the development of cancer, but the underlying mechanisms were still elusive." (PMID 30728352, 2019). "Importantly, opposing effects of different asporin alleles have recently been reported in prostate cancer." (PMID 27409832, 2016). "Stromal ASPN expression was observed in 82% of prostate cancer metastases, and over 50% of metastases were low/ultralow for both HER2 and HER3 and had stromal ASPN expression." (PMID 40857406, 2025). "While ASPN expression is restricted to the stroma of prostate cancer metastases, NRG1 expression has been reported in cancer cells." (PMID 40857406, 2025). "HER2/HER3 signaling was also reproducible in human prostate cancer cells treated with conditioned media (CM) from patient-derived prostate CAFs (PCAFs) that express endogenous ASPN, supporting a paracrine interaction model." (PMID 40857406, 2025). "Patients with advanced prostate cancer have detectable levels of ASPN in their blood as well as elevated stromal ASPN expression at metastatic sites." (PMID 40857406, 2025). "Functional studies have shown that secreted ASPN alters prostate cancer cell phenotypes by increasing cell migration and metastatic potential as demonstrated in both the B6CaP and PC3 models." (PMID 40857406, 2025). "Tucatinib, a small molecule inhibitor of HER2, restricts ASPN-induced signaling and prostate cancer cell migration." (PMID 40857406, 2025). "ASPN activates established ErbB-associated pathways, including PI3K, MAPK, and calcium signaling, in multiple prostate cancer cell lines to promote cell migration." (PMID 40857406, 2025). "Consistent with GSEA findings, recombinant ASPN induced activating phosphorylation of HER2 in all prostate cancer cell lines analyzed." (PMID 40857406, 2025). "In summary, our data identify ASPN as a stroma-secreted HER3 ligand that promotes prostate cancer cell migration through HER2/HER3 signaling." (PMID 40857406, 2025). "The role of ASPN-induced activation of HER2/HER3 in prostate cancer has potential for translation to other solid tumors." (PMID 40857406, 2025). "Module 2 includes COL3A1, COL5A2, and NOTCH3, which have been reported to be associated with metastasis in prostate cancer, as well as HEYL, STMN2, and ASPN, which have been implicated in prostate cancer progression." (PMID 39347576, 2024). "The percentage of ASPN+ cells within the stroma adjacent to prostate cancer was significantly increased compared to stroma adjacent to benign prostate." (PMID 33600062, 2021). "In contrast, ASPN+FAP− cells were as equally enriched as ASPN+FAP+ cells in the microenvironment adjacent to cribriform prostate cancer." (PMID 33600062, 2021). "A recent report by Klee and colleagues indicated that serum asporin was upregulated in men with advanced prostate cancer." (PMID 31608236, 2019). "Our research supports that stroma-secreted ASPN binds to HER3 on adjacent prostate cancer cells and induces phosphorylation of its preferential dimerization partner, HER2, thereby activating multiple ErbB-associated downstream signaling pathways and increasing cellular migration." (PMID 40857406, 2025). "Additionally, mouse androgen-responsive (MyC-CaP) prostate cancer cells were treated with recombinant mouse ASPN." (PMID 40857406, 2025).
prostate carcinoma (continued). "ASPN+ cells enriched in cribriform prostate cancer were also THY1+." (PMID 33600062, 2021). "Furthermore, ASPN+ cells adjacent to Gleason grade 4 cribriform prostate cancer expressed significantly higher levels of ASPN per cell compared to ASPN+ cells adjacent to Gleason grade 4 with noncribriform morphologies or Gleason grade 3 prostate cancers." (PMID 33600062, 2021). "Interestingly, ASPN-induced phosphorylation of the ErbB family member EGFR at Y845 or Y1173 was undetectable to low in most prostate cancer cell lines assessed, including LNCaP, VCaP, LNCaPenzaR, VCaPenzaR, DU145, and MyC-CaP, especially in comparison with EGF-induced EGFR activation." (PMID 40857406, 2025). "Although decorin acts as a tumor suppressor and biglycan is regarded as an oncogene, asporin exerts tumor-suppressor function in triple-negative breast cancer but exerts tumor-promotor function in some types of cancer, including breast, pancreatic, colorectal, gastric, and prostate cancer." (PMID 35600399, 2022). "This corresponding loss of ASPN−NT5E+ cells and gain of ASPN+NT5E+ cells without a net change in total NT5E+ cells in the stroma adjacent to cribriform prostate cancer compared to benign adjacent stroma suggests that ASPN was induced in NT5E+ cells in the cribriform prostate tumor microenvironment." (PMID 33600062, 2021). "ENG expression was also dually examined in a subset of cases probed for ASPN expression in stroma adjacent to benign prostate (n = 10) and in Gleason grade 3 (n = 6), Gleason grade 4 with noncribriform morphology (n = 7), and Gleason grade 4 with cribriform morphology (n = 6) prostate cancer." (PMID 33600062, 2021). "Whole slides from radical prostatectomy were examined for ASPN expression in stroma adjacent to benign prostate (n = 21) and in Gleason grade 3 (n = 13), Gleason grade 4 without cribriform morphology (n = 17), and Gleason grade 4 with cribriform morphology (n = 12) prostate cancer." (PMID 33600062, 2021). "Our data demonstrate that ASPN is a previously unidentified activator of HER2/HER3 signaling and HER2-dependent migration in prostate cancer cells, thereby supporting a role for this signaling axis in advanced prostate cancer." (PMID 40857406, 2025). "Collectively, these findings support that extracellular ASPN is an activator of HER2 and HER3 in prostate cancer cells." (PMID 40857406, 2025). "Our study identifies ASPN as a ligand of HER3 and activator of HER2/HER3 signaling in prostate cancer." (PMID 40857406, 2025). "While NRG1β induces significant phosphorylation of EGFR, ASPN activation of EGFR is limited, suggesting that ASPN-induced ErbB signaling in prostate cancer is primarily through HER2 and HER3." (PMID 40857406, 2025). "While CTHRC1+ CAF were slightly elevated, ASPN+ and FAP+ CAF were comparable between ICC/IDC and Gleason pattern 5 prostate cancer." (PMID 36229464, 2022). "Extracellular ASPN regulates the interaction of TGF-β with its receptor and acts as a negative regulator of TGF-β, promoting bone metastasis in prostate cancer cells." (PMID 36011263, 2022). "As ASPN expression was increased in cribriform prostate cancer, this collectively suggests that ASPN expression was induced in NT5E+ASPN− fibroblasts, TNC+ASPN− fibroblasts, and PDGFRβ+ASPN− fibroblasts in the cribriform tumor microenvironment." (PMID 33600062, 2021). "Our findings support a model in which ASPN binds directly to HER3, induces heterodimerization with HER2, and leads to activation of downstream pathway members AKT, ERK, PLCγ, and CAMKII in human and mouse prostate cancer cells." (PMID 40857406, 2025). "Consistent with HER2/HER3 activation, recombinant ASPN induced activating phosphorylations on AKT, ERK, and calcium pathway members (PLCγ, calcium/calmodulin-dependent protein II [CAMKII]) in human and mouse prostate cancer cells." (PMID 40857406, 2025).
prostate carcinoma (continued). "TNC+ cells trended from ASPN− in benign adjacent stroma to ASPN+ in stroma adjacent to Gleason grade 3 and Gleason grade 4 with noncribriform morphology prostate cancer." (PMID 33600062, 2021). "Collectively, these findings indicate ASPN functions as a HER3 ligand to induce cellular migration, and inhibition with anti-HER2 or anti-HER3 ADC therapies highlights potential clinical utility for patients with metastatic castration-resistant prostate cancer that expresses HER2 or HER3." (PMID 40857406, 2025). "Asporin was selected for further investigation based on the following criteria: (a) Asporin acts as an oncogene in pancreatic, colorectal, gastric, and prostate cancer; (b) The roles of asporin in thyroid cancer have not been reported based in searchers of PubMed or Google." (PMID 35600399, 2022). "Within the cancer subtypes examined, the percentage of ASPN+ cells was the highest within stroma adjacent to Gleason grade 4 prostate cancer with cribriform morphology compared to Gleason grade 4 prostate cancer with noncribriform morphologies and Gleason grade 3 prostate cancer." (PMID 33600062, 2021). "A subset of cases probed for ASPN expression were also dually examined for THY1 expression in stroma adjacent to benign prostate (n = 10) and in Gleason grade 3 (n = 6), Gleason grade 4 with noncribriform morphology (n = 6), and Gleason grade 4 with cribriform morphology (n = 7) prostate cancer." (PMID 33600062, 2021). "CTHRC1+, ASPN+, and FAP+ CAF were located peri-epithelial to ICC/IDC and were significantly enriched in ICC/IDC compared to benign prostate as well as Gleason pattern 3 and Gleason pattern 4 non-ICC prostate cancer." (PMID 36229464, 2022).